RNU7-92P (RNA, U7 small nuclear 92 pseudogene)
Gene: Small nuclear RNA gene on chromosome 20 (47,904,348 to 47,904,423, forward strand). Ensembl gene ENSG00000238785.
Homologues: Orthologues: dog U7 (64% identical). Paralogues in human: RNU7-173P (97% identical), RNU7-144P (87% identical), RNU7-104P (66% identical), RNU7-157P (64% identical), RNU7-65P (64% identical), RNU7-79P (64% identical), RNU7-80P (64% identical), RNU7-11P (63% identical), RNU7-13P (63% identical), RNU7-18P (63% identical), RNU7-25P (63% identical), RNU7-2P (63% identical), and 142 more.